GAS6 (growth arrest specific 6)
Diseases named in the same sentence as GAS6 in open-access papers (continued):
Sharing a sentence is not in itself a finding about the gene and the disease.
schwannoma (4 papers, 2014 to 2018). A benign, usually encapsulated slow growing tumor composed of Schwann cells. "Another study revealed that the underlying mechanism of schwannoma cell proliferation after Gas6/Axl interaction involves Src, focal adhesion kinase (FAK) and NF-κB." (PMID 29386018, 2018). "GAS6, a vitamin K-dependent protein, was shown to regulate cell adhesion in different cells such as endothelial cells and schwannoma cells." (PMID 27999286, 2016). "In addition, GAS6-AXL signaling has recently been shown to increase Schwannoma cell matrix adhesion and survival, further arguing for an involvement of AXL in Schwann cell tumorigenesis." (PMID 25551830, 2014).
acute lymphoblastic leukaemia (3 papers, 2021 to 2025). "A previous study using acute lymphoblastic leukaemia cell lines found that prolonged GAS6 exposure for over 18 h led to preferential expression of a lower molecular weight partially glycosylated form of MERTK compared to control samples where the fully glycosylated form was predominant." (PMID 37958886, 2023).
breast tumors (3 papers, 2008 to 2020). "In breast tumors, Gas6 is highly expressed in pre-invasive lesions associated with increased infiltrating macrophages." (PMID 31963783, 2020).
cardiac hypertrophy (3 papers, 2023 to 2024). "Gas6 acts through the ERK pathway to drive cardiac hypertrophy, and the reversal of hypertrophy was shown with ERK inhibitor treatment." (PMID 39684449, 2024). "We previously demonstrated that the expression of GAS6 was upregulated in human dilated cardiomyopathy, and Gas6 knockout in mice mitigated cardiac hypertrophy, fibrosis and contractile dysfunction." (PMID 36635690, 2023). "Our previous study had demonstrated that Gas6 knockout would alleviate cardiac hypertrophy, fibrosis and contractile dysfunction." (PMID 36635690, 2023). "Genetic ablation of GAS6 in mice protects against cardiac hypertrophy and dysfunction." (PMID 36635690, 2023). "However, genetic ablation of GAS6 alleviated cardiac hypertrophy and improved cardiac function induced by pressure overloading." (PMID 36635690, 2023).
chronic inflammatory demyelinating polyneuropathy (3 papers, 2010 to 2019). "Gas6 protein concentration in CSF was also found elevated in patients with chronic inflammatory demyelinating polyneuropathy (CIDP)." (PMID 31485279, 2019).
depression (3 papers, 2023 to 2025). "Gas-6 induced neuronal pathways therapy holds promise for clinical significance in treating depression." (PMID 39027663, 2024). "Serum levels of testosterone, estradiol, and depression risk biomarkers (thyroid hormone, lipids, hs-CRP, Tenascin-C [TNC], GDF15, KLF4, Gas6, and sgp130) were measured." (PMID 36635686, 2023). "Mechanisms including inflammation reduction, oxidative stress modulation, sphingolipid regulation, and vitamin K-dependent protein signaling (e.g., GAS6 and osteocalcin) were discussed based on indirect evidence and require further investigation in depression-specific contexts." (PMID 40428819, 2025).
esophageal cancer (3 papers, 2019 to 2024). A primary or metastatic malignant neoplasm involving the esophagus. "In summary, Gas6 can be regarded as a clinically valuable prognostic marker and a potential therapeutic target for esophageal cancer." (PMID 39451556, 2024). "Gas6 is closely associated with the progression of many malignant tumors; however, the role of Gas6 in the progression of esophageal cancer is unclear." (PMID 39451556, 2024). "In the present study, we constructed ESCC cells with stable Gas6 knockdown via lentiviral transfection to observe the mechanism of Gas6 in esophageal cancer progression." (PMID 39451556, 2024). "We examined the expression level of Gas6 in esophageal cancer cells by performing Western blotting, and the results showed that Gas6 was significantly expressed in KYSE150 and TE1 cells, which is consistent with our previous findings." (PMID 39451556, 2024). "Here, we report that the knockdown of Gas6 inhibited esophageal cancer cell proliferation, migration, and invasion." (PMID 39451556, 2024). "In this study, we aimed to reveal the role of Gas6 in esophageal cancer and elucidate the possible molecular mechanisms." (PMID 39451556, 2024). "Taken together, the findings confirm that Gas6 knockdown can inhibit esophageal cancer progression and can exert anti-tumor effects on esophageal cancer through the PI3K/AKT pathway." (PMID 39451556, 2024). "The present study demonstrates that QGS inhibits invasion and migration of ESCC cells by regulating the Gas6/AXL signaling pathway and thereby causing a decrease in PI3K/AKT and NF-κB signaling, preventing metastasis of esophageal cancer." (PMID 31110076, 2019). "Our previous protein chip results showed that QGS can reduce the expression of Gas6 of esophageal cancer cells (unpublished data)." (PMID 31110076, 2019). "It has been reported that Gas6 promotes the development of esophageal cancer, Gas6 expression is essentially the same as Axl and is maximally up-regulated in invasiveness and lymph node metastasis of esophageal cancer." (PMID 31110076, 2019). "The results showed that the Gas6, Axl, and Gas6/Axl complex in the control group were highly expressed in the esophageal cancer cell membrane." (PMID 31110076, 2019). "Here, we demonstrated that Gas6 knockdown inhibited esophageal cancer cell migration and invasion." (PMID 39451556, 2024). "Therefore, we speculated that Gas6 might play a pro-esophageal cancer role through the PI3K/AKT pathway." (PMID 39451556, 2024). "Thus, Gas6 knockdown may exert anti-esophageal cancer effects by inhibiting the PI3K/AKT pathway." (PMID 39451556, 2024). "However, the role and mechanism of Gas6 in esophageal cancer remain largely unknown." (PMID 39451556, 2024). "To explore the relationship between Gas6 and the PI3K/AKT pathway in esophageal cancer, we examined the correlation between Gas6 and the PI3K gene family in esophageal cancer in the TCGA database with the online tool GEPIA2." (PMID 39451556, 2024). "The results and references in the present study confirm that GAS6/AXL is an important pathway affecting the invasion and metastasis of esophageal cancer." (PMID 31110076, 2019). "In addition, Gas6 knockdown can inhibit the expression of PI3K/AKT-pathway-related proteins, which, in turn, exert anti-esophageal cancer effects." (PMID 39451556, 2024). "Study is in order to confirm that QGS can regulate Gas6/Axl and its downstream signaling pathway, thereby inhibiting cell invasion and migration, so as to provide theoretical basis for QGS as a treatment for esophageal cancer." (PMID 31110076, 2019). "However, although this study analyzed the role of Gas6 in ESCC, confirmed that Gas6 knockdown may inhibit esophageal cancer migration and invasion through the PI3K/AKT pathway, and provided relevant evidence, its limitations still need to be acknowledged." (PMID 39451556, 2024).
experimental autoimmune encephalomyelitis (3 papers, 2020). An autoimmune demyelinating disease of the central nervous system that is produced experimentally in animals by the injection of homogenized brain or spinal cord in Freund's adjuvant. "Direct administration of Gas6 into the CNS was protective in experimental autoimmune encephalomyelitis, whilst deletion of Gas6 enhanced inflammation and delayed recovery." (PMID 32722558, 2020). "When MOG-induced experimental autoimmune encephalomyelitis was performed in Gas6−/− mice, worse clinical scores, delayed recovery from damage, a higher expression of pro-inflammatory molecules, and a significant increase of macrophages infiltration were observed." (PMID 33347509, 2020). "During experimental autoimmune encephalomyelitis (EAE), the mRNA expression of MerTK, Gas6, and Axl significantly increase, whereas Tyro3 and ProS1 remain unchanged." (PMID 33121494, 2020).
hepatic (3 papers, 2019 to 2023). "GAS6 deficiency has been reported to reduce the expression of TNF-α and MCP-1 and was suggested to prevent liver inflammation, steatohepatitis, and fibrosis in mice." (PMID 34734092, 2021). "In patients with hepatitis, serum levels of Gas6 and Axl are significantly elevated, and it is hypothesized that Gas6/Axl play a key role in fibrosis formation and chronic liver disease progression." (PMID 38259511, 2023). "We propose that increase level of endogenous Gas6 may emerge as a potential target to reduce ALI later, just as the findings in hepatic IR." (PMID 31318922, 2019).
hyperlipidemia (3 papers, 2023 to 2025). "There was a beneficial effect of VitK supplementation on the management of hyperlipidemia‐associated inflammatory events via activating VitK‐dependent Gas6 protein." (PMID 37051359, 2023). "Specifically, hyperlipidemia and Gas6/AXL complex levels were positively correlated, and identified as risk factors, with odds ratios (OR) of 157.045 (7.171–3439.520, p < 0.001) and 3.307 (1.209–9.051, p = 0.020), respectively." (PMID 40933570, 2025). "Multivariate logistic regression analysis indicated that STEMI was associated with the Gas6/AXL complex, hyperlipidemia, and LVEF." (PMID 40933570, 2025). "Notably, GAS6 has been reported to attenuate vascular calcification and hyperlipidemia through modulation of the AMPK pathway." (PMID 40872581, 2025). "Additionally, the Gas6/AXL complex, along with hyperlipidemia, serves as a risk factor for STEMI." (PMID 40933570, 2025).
liver cirrhosis (3 papers, 2022 to 2025). "These methods were used by Holstein and colleagues from German Cancer Research Center (DKFZ) to show HSC activation by TGF-β and Growth Arrest-Specific 6 (GAS6) (human growth inhibitor-specific 6)/AXL pathways in liver cirrhosis and cancer." (PMID 40142664, 2025).
lymphoma (3 papers, 2016 to 2020). A malignant (clonal) proliferation of B- lymphocytes or T- lymphocytes which involves the lymph nodes, bone marrow and/or extranodal sites. "Coculture of M(IFN-γ/LPS) macrophages with apoptotic lymphoma cells significantly increased the expression of Mrc1, Timp2, Cd36, Pparg and Gas6, whereas the expression of Tnf and Il6 were significantly decreased." (PMID 28157210, 2017). "In these contexts, it is noteworthy that Gas6 is upregulated in SS-TAMs, at least in BL2 xenografts, suggesting that these macrophages of the lymphoma microenvironment are armed with both receptor and ligand for such responses." (PMID 32973744, 2020). "By contrast, expression of mouse Mertk and Gas6 by murine lymphoma cells (MycEd1) was low or absent." (PMID 32973744, 2020). "The upregulation of Gas6, Mrc1, Cd36 and Timp2 expression by M(IFN-γ/LPS) macrophages was specific for coculture with apoptotic cells, as coculture with unstimulated or Bcl-2-transfected lymphoma cells did not lead to a significant upregulation of these genes." (PMID 28157210, 2017).
metastatic tumors (3 papers, 2016 to 2025). "Consistently, administration of GAS6 or TAM receptor inhibitors leads to rejection of metastatic tumors." (PMID 35967396, 2022). "Together these data suggest that endogenous GAS6 and Mer receptor signaling contribute to the establishment of PCa CSCs in the bone marrow microenvironment, which may have important implications for targeting metastatic disease." (PMID 27028863, 2016). "We found that ligand-receptor pairs between metastatic tumors and immune cells were significantly upregulated in lymph nodes compared with primary tumors (CCL10-CXCR3, IL34-CSF1R, GAS6-MERTK), indicating that these pathways are critical for the immune response to tumors." (PMID 40881692, 2025).
ovarian tumor (3 papers, 2017 to 2025). "Metastatic ovarian tumor cells are critically associated with the GAS6/AXL signaling pathway for metastatic colonize." (PMID 31700829, 2019). "GAS6 mRNA in ovarian tumor tissues was elevated more in stage I, II or low stages than stages III, IV." (PMID 31700829, 2019). "In metastatic ovarian tumor cells, AXL expression is dramatically increased and accumulating of these cells to form colony is noticeably depend on the GAS6/AXL signaling pathway." (PMID 31700829, 2019). "Patients with higher expression of GAS6 in ovarian tumors failed to respond effectively to neoadjuvant chemotherapy, had poor progression-free survival and overall survival as compared to those with lower GAS6 expression levels." (PMID 40813689, 2025).
pancreatic ductal adenocarcinoma (3 papers, 2016 to 2020). An infiltrating adenocarcinoma that arises from the epithelial cells of the pancreas. "Recent studies employing Gas6 neutralizing antibodies, GMAB1 and GMAB2, shown to decrease tumor growth in the pancreatic ductal carcinoma by blocking autocrine Gas6-Axl signaling clearly support the rationale to target Gas6." (PMID 27916840, 2016).
renal fibrosis (3 papers, 2020 to 2022). A final common manifestation of a wide variety of chronic kidney diseases characterized by glomerulosclerosis and tubulointerstitial fibrosis. "Poricoic acid upregulates Gas6/Axl signaling in AKI, reducing oxidative stress and inflammation, and reducing renal fibrosis by downregulating Gas6/Axl signaling in CKD." (PMID 35673387, 2022). "Interestingly, poricoic acid A and melatonin could upregulate growth arrest-specific 6 (Gas6)/Axl signaling to reduce oxidative stress and inflammation in the AKI disease status and further downregulate Gas6/Axl signaling to attenuate renal fibrosis in the CKD disease status." (PMID 35924053, 2022).
steatosis (3 papers, 2019 to 2024). Increased lipid within the cytoplasm of cells. "Amongst all three receptors, AXL exhibits higher affinity towards Gas6 and the Gas6/AXL pathway is known to be involved in the development of steatosis to fibrosis." (PMID 34944593, 2021). "Thus, this study highlights the possible deleterious effect of Gas6 in the progression of steatosis to steatohepatitis and fibrosis." (PMID 31583026, 2019). "They observed that blocking of the Gas6/AXL pathway significantly reduced triglyceride content, and overall steatosis score in mice fed on a high fat diet." (PMID 34944593, 2021).
systemic inflammatory response syndrome (3 papers, 2010 to 2021). SIRS is a serious condition related to systemic inflammation, organ dysfunction, and organ failure. "Components of the GAS6/TAM system increase in a diverse spectrum of inflammatory conditions, including septicemia and septic shock; but also in systemic inflammatory response syndrome (SIRS) in the absence of infection." (PMID 33810394, 2021).
triple-negative breast carcinoma (3 papers, 2020 to 2024). An invasive breast carcinoma which is negative for expression of estrogen receptor (ER), progesterone receptor (PR), and human epidermal growth factor receptor 2 (HER2). "Axl, which is also activated by Gas6 and highly expressed in triple-negative breast cancer cells, promotes EMT." (PMID 32432570, 2020).
vasculitis (3 papers, 2013 to 2019). "In contrast, in mouse models of endotoxinemia, vasculitis, and heart transplantation, Gas6 promotes leukocyte extravasation, inflammation, and thrombosis by enhancing interactions between endothelial cells, platelets, and leukocytes." (PMID 31318922, 2019). "A recent study of GAS6 SNPs showed linkage with traits of SLE, including vasculitis (rs1803628) and thrombocytopenia (rs8191974), suggesting that larger studies could find associations between these genes and the development of certain disease traits." (PMID 23497733, 2013).
alopecia (2 papers, 2023). Hair loss usually from the scalp. "In line with this hypothesis is that in our study population, the patients complaining of hair loss showed decreased levels of Gas6 and sAxl compared to all others." (PMID 37047229, 2023). "We also evaluated the association of the Gas6/sTAM system with the development of hair loss." (PMID 37047229, 2023). "Interestingly, lower levels of Growth Arrest-Specific 6 (Gas6) and its soluble receptor Axl (sAxl) were associated with a history of alopecia." (PMID 37445634, 2023). "Second, we did not measure the baseline levels of Gas6 and sTAM to understand whether these biomarkers may also have a pathogenetic role in the development of hair loss." (PMID 37047229, 2023).
anaemia (2 papers, 2013 to 2016). "Treatment of mice with recombinant Gas6 hastens their recovery from both acute hemolytic anemia and acute blood loss anemia." (PMID 27834816, 2016).
asthma (2 papers, 2017 to 2022). "At present, a total of 17 VKdPs have been identified in the human body, and these VKdPs play an important role in a variety of diseases, among which periosteal and Gas6 have been found to be beneficial to asthma patients." (PMID 35722472, 2022). "Growth-arrest-specific 6 (GAS6) and protein S are the ligands that bind and activate the TAM receptors, and GAS6 showed higher expression in subjects with severe asthma during exacerbation." (PMID 29177020, 2017).
Behçet’s disease (2 papers, 2016 to 2025). "Two SNPs within GAS6 and PROS1 genes contributing to the genetic susceptibility of Behçet’s disease were associated with the reduced transcription of corresponding genes." (PMID 40044635, 2025). "Likewise, single-nucleotide polymorphisms in GAS6- and PROS1-encoding genes are associated with Behçet’s disease, a condition characterised by multisystemic inflammations with recurrent ocular symptoms and ulcers in different organs." (PMID 40044635, 2025). "In several inflammatory and autoimmune diseases, including inflammatory bowel disease, MS, SS, Behcet’s disease, SLE, and psoriasis, plasma levels of GAS6 and PROS1 were lower than in healthy individuals." (PMID 40044635, 2025).
endometrial cancer (2 papers, 2016 to 2023). Primary or metastatic malignant neoplasm involving the endometrium (mucous membrane that lines the endometrial cavity). "Western blot analysis showed that exogenous GAS6 induced phosphorylation of AXL in both endometrial cancer cell lines." (PMID 27764792, 2016). "Whether secretion of growth factors (TGFβ, GAS6, FGF5 and HGF), cytokines and chemokines (IL-6, CXCL9) from CAFs,32 may affect aggressiveness and thereby associate with recurrence of endometrial cancer, is not known and could be investigated in future studies." (PMID 37146405, 2023).
endotoxemia (2 papers, 2016 to 2022). "Endogenous Gas6 has a homeostatic role by acting on macrophages and plays a beneficial role in murine models of endotoxemia." (PMID 27788141, 2016).
head and neck cancer (2 papers, 2017 to 2019). A primary or metastatic malignant neoplasm affecting the head and neck. "In SCC-25 head and neck cancer cells expressing both Tyro3 and Axl, Western blotting showed that both natural TAM ligands ProS1 and Gas6 rapidly stimulated Tyro3 and Erk kinase phosphorylation, with ProS1 eliciting a greater effect." (PMID 31766614, 2019). "As shown, NNMT, FLI1, SLPI, LAMP3, SERPINA1, GAS6, and CD274 have been often used as biomarkers for OSCC or head and neck cancer, while other genes listed have seldom been investigated in oral cancer and may be considered as novel biomarkers for OSCC prevalence and treatment." (PMID 28286742, 2017).
head and neck squamous cell carcinoma (2 papers, 2016 to 2024). A squamous cell carcinoma that arises from any of the following anatomic sites: lip and oral cavity, nasal cavity, paranasal sinuses, pharynx, larynx, and salivary glands. "Our results also show that Gas6 signaling increases TGF-β2 expression, which induces dormancy in head and neck squamous cell carcinoma (HNSCC) and breast cancer cells." (PMID 27819283, 2016).